Y_RNA (Y RNA )
Gene: Miscellaneous RNA gene on chromosome 17 (49,416,744 to 49,416,850, reverse strand). Ensembl gene ENSG00000207127.
Homologues: Orthologues: chimpanzee Y_RNA (98% identical), macaque Y_RNA (96% identical). Paralogues in human: RNY1 (85% identical), Y_RNA (84% identical), Y_RNA (83% identical), Y_RNA (82% identical), Y_RNA (81% identical), Y_RNA (80% identical), RNY1P11 (79% identical), RNY1P8 (79% identical), Y_RNA (79% identical), RNY1P5 (78% identical), Y_RNA (78% identical), RNY1P12 (77% identical), and 95 more.